S100A11 (S100 calcium binding protein A11)
Diseases named in the same sentence as S100A11 in open-access papers (continued):
Sharing a sentence is not in itself a finding about the gene and the disease.
adenocarcinoma (1 paper, 2015). A common cancer characterized by the presence of malignant glandular cells. "S100A11 levels were significantly higher in adenocarcinomas with KRAS mutations and strong proliferating activity (P = 0.038 in the Kruskal-Wallis test)." (PMID 26544866, 2015). "Among the three subtypes, S100A11 levels were significantly higher in adenocarcinomas with KRAS mutations and strong proliferating activity." (PMID 26544866, 2015).
neurodegenerative disease (1 paper, 2025). A disorder of the central nervous system characterized by gradual and progressive loss of neural tissue and neurologic function. "In particular, SRC-1-KO mice express significantly lower S100A6 and S100A11, and both genes have been demonstrated neuroprotective effects in neurodegenerative diseases." (PMID 40882002, 2025).
S100A11 also shares sentences with these, for which no sentence is quoted: COVID-19 (3 papers); astrocytoma (2); cholangiocarcinoma (2); intraductal papillary mucinous neoplasm (2); Obesity (2); allergic asthma (1); amyotrophic lateral sclerosis (1); atherosclerosis (1); autoimmune disease (1); autoimmune encephalitis (1); autoimmune pancreatitis (1); carcinosarcoma (1); cervical squamous cell carcinoma (1); Crohn disease (1); depression (1); dry eye (1); Eczema (1); endocarditis (1); endometriosis (1); epilepsy (1); esophageal cancer (1); laryngeal squamous cell carcinoma (1); low grade glioma (1); lung fibrosis (1); malignant pleural mesothelioma (1); nasopharyngeal carcinoma (1); non-alcoholic steatohepatitis (1); proliferative diabetic retinopathy (1); renal fibrosis (1); scleroderma (1).
A further 6 diseases each share a sentence with S100A11 in 1 paper.